APC (APC regulator of Wnt signaling pathway)
Diseases named in the same sentence as APC in open-access papers (continued):
Sharing a sentence is not in itself a finding about the gene and the disease.
tumor (continued). "Additionally, among the top 20 mutated oncogenic genes in the low-DR group, we identified mutations that closely correlated with tumour progression, such as those in APC and FAT3,71,72 indicating a more malignant characteristic of the tumours in low-DR patients." (PMID 38507875, 2024). "Although this remains to be formally tested, a possible tumour suppressive role may arise through its relationship with SKP2, where EMI1 prevents the uncontrolled degradation of SKP2 by APC/CCDH1, thereby allowing SCFSKP2 to regulate Cyclin E1 abundance preventing its aberrant accumulation." (PMID 39358461, 2024). "Deletion of USP7 in cancer cell lines and organoids inhibits WNT activation by restoring β-catenin ubiquitination specifically in APC-mutated, but not wild-type (WT), cells, suggesting that USP7 may represent a tumor-specific drug target." (PMID 36669491, 2023). "In contrast, Hes1, a Notch target gene normally associated with stemness and absorptive cell differentiation, and Phlda2, a growth restriction gene in development and a tumor suppressor, were upregulated in APC and AOM/DSS tumor cells, but not in squamous cells." (PMID 35600339, 2022). "Importantly, VilCreER;Apcfl/+;KrasG12D/+;Alk5CA tumours exhibited high expression of the Alk5CA transgene and prominent p-SMAD3 staining, in contrast to APC-deficient tumours lacking Kras mutation." (PMID 36477656, 2022). "Through its synergy with Apc/APC‐dependent activated Wnt, TRα1 accelerates tumor growth and participates in tumor progression, including cancer spreading and possibly integrating other tumor processes not yet established." (PMID 36217307, 2022). "Moreover, literature reports that KRAS and APC mutations are the principal causes of the CRC onset, but they are not related to the tumor stage or location." (PMID 34599254, 2021). "However, in line with the lack of tumor formation in the brains of GL mice, we did not observe a significant increase in the abundance of selected Wnt and Shh targets (APC, GLI2, AXIN2, MYCN, MYC)." (PMID 34801069, 2021). "We noticed that LARGE2 expression in full-blown CRC and patient-derived PDTOs was strongly elevated when compared to normal tissues and pre-malignant APC-MCR mutant ADOs, which might reflect an upregulation of tumor cell intrinsic Wnt activity during tumor progression." (PMID 32586342, 2020). "Inactivating mutations of the tumor suppressor Adenomatosis Polyposis Coli (APC), which are found in familial adenomatosis polyposis and in 80% of sporadic colorectal cancers (CRC), result in constitutive activation of the Wnt/β-catenin pathway and tumor development in the intestine." (PMID 31109112, 2019). "N-WASP deletion did not affect tumor formation in the APC+/− Kras G12D model." (PMID 31608298, 2019). "Besides, inactivation of TGF-β pathway by deleting TGFBR2 in combination of APC tumor suppressor deletion could result in rapid onset of invasive PCa, which implied TGFBR2 might exert tumor suppressive effect in prostate." (PMID 29699590, 2018). "In contrast, the Wnt/β-catenin signal is activated in tumour cells when APC is non-functional." (PMID 30181617, 2018).
tumor (continued). "We excised tumor lesions or corresponding healthy mucosa from the colon of DSS-treated APC+/min and DSS-treated WT mice, respectively: mRNA analysis by qPCR indicated a significant increase in the expression of the β3 subunit in tumor lesions of DSS-treated APC+/min mice." (PMID 30140377, 2018). "Notably there were no mutations detected in APC and KRAS in 3 metastatic samples although primary tumours from the same patients were carrying mutations in this genes." (PMID 30231850, 2018). "Our observation in terms of homogeneous and heterogeneous methylation profiles might help to explain why the methylation of APC, RASSF1A, and RARβ genes with a homogeneous pattern have been detected at high frequency and are used successfully in detecting various tumour types as well as MRD." (PMID 30154364, 2018). "APC is a tumor-suppressor gene and has an important role in the negative regulation of the Wnt signaling pathway, a key pathway that promotes cell proliferation and migration due β-catenin overexpression, which induces the transcription of oncogenes such as c-Myc." (PMID 30376837, 2018). "The results demonstrated that the P16, RASSF1A and APC methylation with low sensitivity (< 0.5) and AUC (< 0.8) could not distinguish lung cancer and non-tumor samples well." (PMID 28977861, 2017). "However, in our previous study, APC was not the most frequently mutated gene in 50 colorectal (CRC) tumors, nor did it have the highest mutated allelic frequency within one tumor." (PMID 29069792, 2017). "In addition to APC methylation, we also investigated a possible role of non-APC-mutated WNT pathway gene mutations as a ‘second hit' in one-hit- APC mutation tumours using the TCGA CRCs that were available with whole-exome-sequencing data." (PMID 27302369, 2016). "Thus, our data do not support methylation of the APC promoter as a ‘second hit' in one-hit APC tumours." (PMID 27302369, 2016). "Furthermore, in silico analysis demonstrated that miR-23b, miR-24-2, miR-141, and miR-449 act as tumour suppressors by inhibiting translation of CTNNB1 mRNA, while miR-150 was proposed to be acting as an oncomiR by modulating adenomatous polyposis coli (APC)." (PMID 26064134, 2015). "The peripheric portion of the tumor presented a different profile: 5/84 CpG sites were aberrantly methylated, from which 2 sites were shared with the center portion, that is, MSH3 and MLH1, and 3 sites were exclusively methylated in the tumor periphery, that is, MSH6, MGMT, and APC." (PMID 25544907, 2014). "However, a higher degree of APC promoter methylation in tumor tissues does not appear to be responsible for a poorer overall survival rate, as has been reported in previous studies." (PMID 24765201, 2014). "In this review, we focus on how the remarkable lack of structure in the large central domain of APC may facilitate its tumor suppressor function in the Wnt/β-catenin cascade." (PMID 21859464, 2011). "It was also reported thatwhole animal hemizygous knockout of PPARγ had no affect on tumor number or size in APC+/Min mice, an observation that is atvariance with the notion that PPARγ promotes tumor formation in mice that containactivating germ line mutations in the Wnt/APC/β-catenin pathway." (PMID 18615192, 2008).
tumor (continued). "Importantly,PPARβ/δ-dependent tumor vascularization was not restricted to ectopic tumor models, but was also seen with intestinal adenomas in APC+/min mice which showed disorganized microvessels specifically in a Pparb−/− background." (PMID 18497874, 2008). "No increase in tumor size was observed in thesecond report, which was, therefore, not entirely consistent with the first.Moreover, two subsequent reports failed to reproduce the effect ofthiazolidinediones in APC+/Δ1309 or APC+/Min mice." (PMID 18615192, 2008). "In colorectal cancer, several tumour suppressor genes have been identified to be epigenetically inactivated by CpG island promoter hypermethylation, including the DNA mismatch repair gene MLH1, the gatekeeper APC, and the cell cycle inhibitor CDKN2A, to mention some." (PMID 18346269, 2008). "However, mutations typically responsible for deregulated β-catenin/TCF activity in other tumours, that is, in APC, AXIN, BTRC and CTNNB1, have not been found in TCC to date." (PMID 12799639, 2003). "Mice with truncation mutations in APC which preserve the SAMP regions do not develop tumors, whereas truncations removing the SAMP sites cause adenomatous polyposis, highlighting the importance of the binding of APC to Axin 1 and 2 for tumor suppression via destruction of β-catenin." (PMID 32823838, 2020). "However, we found promoter methylation of the APC gene in 40% of EOCRC tumours, a higher rate than reported in overall CRC, suggesting that specific methylation at the APC gene promoter may play an important role in EOCRC, despite lower methylation more generally." (PMID 33352971, 2020). "Furthermore, APC (p < 0.0001), ASXL1 (p < 0.0001), DNMT3B (p = 0.001), PARP4 (p = 0.002), MET (p = 0.01), TOP1 (p = 0.01), KDR (p = 0.01), SRC (p = 0.01), PAK1 (p = 0.015), ALK (p = 0.02), and MYC (p = 0.03) alterations were found to be more common in tumor samples from AO mCRC patients." (PMID 33194656, 2020). "In one tumor, with ALK positive reaction, negative nuclear reaction against β-catenin and the lack of CTNNB1 mutation, next generation sequencing revealed a presence of pathogenic variant c.3366_3369del in the APC gene, with homozygous deletion leading to inactivation of both copies in tumor cells." (PMID 30523493, 2019). "This pathway involves the accumulation of inhibitory mutations at the level of tumor-suppressor genes and activating mutations at the level of oncogenes and are associated with colorectal tumors exhibiting MSS, non-CIMP, CIN, absent KRAS and BRAF mutations, and APC mutations." (PMID 29652830, 2018). "Further, we analyzed whether the methylation status of P16, RASSF1A, APC, RARβ, DAPK, CDH13, and MGMT there were differences in the characteristics of gene methylation in different tumor stages (early stage vs. advanced stage) and tumor histotypes (SCC vs. AC)." (PMID 28404957, 2017). "Thus, if APC was not necessary for tumour development in patients with a germ-line deletion of the APC gene, one would expect loss of heterozygocity (LOH) as the mechanism of inactivation of the second APC allele, because it is spontaneously more frequent than a mutation." (PMID 22509309, 2012).
tumor (continued). "Thus, it is intriguing to speculate that restoring IGFBP3 expression and/or use of demethylating drugs could contribute to new therapeutic strategies for HB, especially with the existence of additional epigenetically silenced genes in this tumor type, such as HHIP, RASSF1, SOCS1, APC and CASP8." (PMID 22401581, 2012). "APC and CDKN2A are two hypermethylated gene promoters that can discriminate between the tumours of liver cancer and the surrounding nontumorous liver tissues." (PMID 41011154, 2025). "In conclusion, this study demonstrates that patients with mCRC with PM have distinct clinical and molecular characteristics compared with those without PM, including differences in histologic grade, tumor location, and presence of MED12 and APC alterations." (PMID 38329392, 2024). "Although the detailed mechanisms of BRAF and APC loss and GNAS expression in this study are not fully understood, shifts in these important signaling pathways involved in tumorigenesis may contribute to changes in the tumor environment and could be associated with the ICI response." (PMID 39796090, 2024). "In metastatic but not in primary tumor cells, eustress and inhibition of JNK reduced APC, β-catenin, and pJNK protein." (PMID 39200280, 2024). "Our previous data using CRC cell lines and organoids showed that USP7 is essential for pathological WNT activation in APC mutant cells but not physiological WNT signaling in normal cells, suggesting that USP7 can be used as tumor-specific drug target." (PMID 36669491, 2023). "For example, we found that E-cadherin, ESRP1 staining was greatly increased in tumors from CDX2;APC;PID mice, whereas Msi1 was decreased in these tissues, relative to tumor tissue from animals lacking PID expression." (PMID 30150766, 2018). "Caspase 3 staining was not prominent in tumor tissue from either CDX;APC;PID− or CDX;APC;PID + mice." (PMID 30150766, 2018). "Homogeneous LOH of APC was observed in two tumors (EAC1 and 2), different subclones with and without LOH of APC were observed in EAC3 and 4, whereas one tumor (EAC5) was not informative for the APC locus." (PMID 28376920, 2017). "Of 21 tumours with the c3924_3925insA for which the LOH status was also known, 6 (29%) showed APC LOH and 15 (71%) did not." (PMID 24416237, 2014). "In the absence of APC function, the WNT pathway is activated through β-catenin, leading to the transcription of a battery of tumor-promoting genes, including Myc." (PMID 25288683, 2014). "Hazard ratios (HR) and 95% confidence intervals (CI) of prostate cancer mortality for methylation of APC and GSTP1 in the non-neoplastic tissue adjacent to the tumour (NTAT)." (PMID 23874531, 2013). "At the same time despite of marked methylation in tumor DNA, no methylation of BRCA1 and APC was seen in PB DNA of 4.3% and 2.7% of the patients respectively." (PMID 22129206, 2011). "PMR values of APC (r=0.398, P=0.001), RASSF1A (r=0.551, P<0.001), but not of ESR1 (r=0.078, P=0.52), were positively correlated with levels of the tumour marker CA15.3." (PMID 19367284, 2009).
tumor (continued). "Tumor size also differed significantly between APC; KRAS without DSS and both DSS-treated groups (P < 0.01 and P < 0.01), but not between APC; KRAS with DSS and APC with DSS (P = 0.11)." (PMID 41285904, 2025). "However, upon DSS administration, multiple tumors formed in the distal colon tumors, and APC; KRAS mut mice developed small proximal colon tumors even without DSS treatment, with both tumor size and number increasing upon DSS administration." (PMID 41285904, 2025). "Tumor cells were positive for PTH and APC but negative for galectin-3 and PGP9.5." (PMID 38363524, 2024). "However, in some cases, SNVs were seen only in the tumor and not in the corresponding CSF cfDNA, including SNVs in ROBO1, APC, PIK3CA or ARID1A." (PMID 37444642, 2023). "Multivariate analysis of data acquired on large colonic sections containing both tumour and normal adjacent tissue (NAT) did not distinguish between APC and APC KRAS tumours, indicating that the observed metabolic differences between tumours and NAT exceed the impact of oncogenic Kras expression." (PMID 37580540, 2023). "Taken together, the noted signaling differences and lack of progression to adenocarcinoma in CDX2;APC;PID mice suggests that Group I Pak kinase activity is a key factor in tumorigenesis and the expression of PID peptide is sufficient to impede tumor progression in this CRC mouse model." (PMID 30150766, 2018). "Notably, known CRC drivers (APC, FBXW7, and KRAS) did not segregate according to tumor ploidy status." (PMID 28073006, 2017). "Moreover, we found all CpG sites for RASSF1 and APC, but none for GSTP1, to have significantly higher methylation levels in ER-positive than in ER-negative tumours." (PMID 20565864, 2010).